ENSG00000258417 (novel protein)
Gene: Protein-coding gene on chromosome 8 (132,024,238 to 132,085,655, reverse strand). Ensembl gene ENSG00000258417.
Genetic constraint (gnomAD): Loss-of-function variants: 52 observed, 51.13 expected, observed/expected ratio (o/e) 1.02, 90% interval 0.81 to 1.28. Missense variants: 792 observed, 698.25 expected, observed/expected ratio (o/e) 1.13, 90% interval 1.07 to 1.2. Synonymous variants: 316 observed, 267.07 expected, observed/expected ratio (o/e) 1.18, 90% interval 1.08 to 1.3.